LDHA (lactate dehydrogenase A)
Diseases named in the same sentence as LDHA in open-access papers (continued):
Sharing a sentence is not in itself a finding about the gene and the disease.
glioblastoma (46 papers, 2013 to 2026). The most malignant astrocytic tumor (WHO grade IV). "In 2017, Michael Koukourakis’ team evaluated the expression of the LDH5 isoenzyme in human glioblastoma tissue, and their results showed that the enzyme is encoded exclusively by the LDHA gene." (PMID 36811010, 2023). "A study in a murine glioblastoma model using neural stem cells showed that these cells have the capacity of tumour formation, and present a metabolic signature associated with a glycolytic phenotype with increased expression of LDHA." (PMID 34298681, 2021). "Our study demonstrated that LDHA enzymes encapsulated in plasma extracellular vesicles activate glioblastoma stemness by enhancing glycolysis." (PMID 40093910, 2025). "In this study, we show that Oxamate, an LDHA inhibitor, enhances radiosensitivity in glioblastoma cells via multiple mechanisms, including delayed DNA repair and increased apoptosis." (PMID 40565174, 2025). "In glioblastoma, LDHA activates the ERK-YAP1/STAT3 axis, upregulating CCL2 and CCL7 to recruit macrophages, which in turn deliver LDHA to tumor cells via extracellular vesicles, forming a tumor-macrophage symbiotic loop that drives progression." (PMID 40734168, 2025). "In this study, we investigated how LDHA inhibition by Oxamate affects radiosensitivity in glioblastoma cells, focusing on DNA repair, stemness, and epithelial–mesenchymal transition (EMT)-related markers." (PMID 40565174, 2025). "In glioblastoma, the Warburg effect drives high glycolytic flux, making cells reliant on LDHA for NAD+ regeneration and lactate production." (PMID 40565174, 2025). "Glioblastoma cells enhance TAM recruitment by activating the LDHA-ERK-YAP1/STAT3 axis, leading to CCL2 and CCL7 secretion, which attracts macrophages into the TME." (PMID 40223940, 2025). "c-Myc has been shown to drive LDHA expression and in glioblastoma patient-derived xenografts was shown to be responsible for increased lactate labeling from hyperpolarized [1-13C]pyruvate." (PMID 39639170, 2025). "Preclinical trials in glioblastoma mouse models, followed by clinical-pathological validations using patient tumor and plasma samples, point to LDHA and its downstream signals as promising therapeutic targets for glioblastoma." (PMID 38443336, 2024). "The results from flow cytometry on these isolated EVs demonstrated that LDHA in glioblastoma patient plasma EVs was significantly higher than that from healthy controls." (PMID 38443336, 2024). "Increasing evidence has shown that LDHA-mediated glycolysis promotes glioblastoma cell proliferation and survival and induces resistance to radiotherapy and chemotherapy." (PMID 38443336, 2024). "We have shown that genetic depletion of LDHA in glioblastoma cells or macrophages extends survival, reduces macrophage infiltration and glioblastoma cell proliferation, and promotes glioblastoma cell survival in mouse models." (PMID 38443336, 2024). "In summary, these results reinforce that the expression of CCL2 and CCL7 in glioblastoma cells/GSCs is regulated by LDHA and that glioblastoma cell CCL2 and CCL7 function as potent macrophage chemoattractants." (PMID 38443336, 2024). "Surprisingly, we noticed that LDHA inhibition in macrophages abolished EMφ CM-induced LDHA upregulation in glioblastoma cells, suggesting a potential for LDHA delivery from EMφ to glioblastoma cells." (PMID 38443336, 2024). "In exploring the connection between LDHA and macrophage biology, we demonstrated that glioblastoma cell LDHA upregulates multiple downstream chemokines, most prominently CCL2 and CCL7, to trigger macrophage infiltration, consistent with previous work." (PMID 38443336, 2024). "Here the authors show that the glycolytic enzyme lactate dehydrogenase-A mediates macrophage-cancer cell crosstalk to promote glioblastoma progression." (PMID 38443336, 2024).
glioblastoma (continued). "In our study, we established that LDHA-mediated glioblastoma cell glycolysis promotes the infiltration of macrophages into the TME, which, in turn, supports tumor progression in glioblastoma mouse models." (PMID 38443336, 2024). "In glioblastoma, silencing LDHA expression leads to reduced glycolysis, slower cell growth, increased apoptosis, and reduced invasion." (PMID 39582531, 2024). "LDHA and its downstream signals, as potential biomarkers, are positively correlated with macrophage density, such as in glioblastoma." (PMID 39464313, 2024). "Next, we performed immunofluorescence for LDHA and Mac-2 (a macrophage marker) in tumors from a cohort of 30 glioblastoma patients and found that LDHA signaling showed a positive correlation with the density of intratumoral macrophages." (PMID 38443336, 2024). "In our study, analysis of scRNA-seq data from glioblastoma patient tumors demonstrated that LDHA is highly expressed by both glioblastoma cells and macrophages." (PMID 38443336, 2024). "To confirm the role of LDHA in glioblastoma cell biology, we performed cell cycle, apoptosis, and proliferation analyses in glioblastoma cells with or without LDHA inhibition." (PMID 38443336, 2024). "We found that LDHA depletion significantly inhibited tumor growth and extended survival in both glioblastoma mouse models." (PMID 38443336, 2024). "To reveal how TAMs upregulate LDHA in glioblastoma cells, we depleted LDHA using shRNAs and inhibited LDHA using FX-11 in EMφ." (PMID 38443336, 2024). "Together, these findings support a pivotal role of glioblastoma cell/GSC LDHA in triggering macrophage infiltration into the glioblastoma TME." (PMID 38443336, 2024). "Together, these results validate the importance of LDHA-regulated tumor-macrophage symbiosis in promoting glioblastoma progression and support a therapeutic potential of targeting this co-dependency in glioblastoma." (PMID 38443336, 2024). "The authors demonstrated that in glioblastoma tissue, LDHA and LDHB are spatially differentially expressed and only a few cells expressed both isoforms." (PMID 36852624, 2023). "Genetic and pharmacological inhibition of LDHA-mediated tumor-macrophage symbiosis markedly suppresses tumor progression and macrophage infiltration in glioblastoma mouse models." (PMID 37886538, 2023). "High levels of lactate and LDHA were detected in highly invasive glioblastomas compared to low invasive GBM, which limited the tumor-infiltrating area." (PMID 38139462, 2023). "Combined profiling and functional studies demonstrate that LDHA-directed ERK pathway activates YAP1/STAT3 transcriptional co-activators in glioblastoma cells to upregulate CCL2 and CCL7, which recruit macrophages into the tumor microenvironment." (PMID 37886538, 2023). "Analysis of tumor and plasma samples of glioblastoma patients confirms that LDHA and its downstream signals are potential biomarkers correlating positively with macrophage density." (PMID 37886538, 2023). "This study highlights the importance of metabolic symbiosis dependent on lactate and lactate dehydrogenase isoforms (LDHA and B) in glioblastoma development." (PMID 36278433, 2022). "Individual CRISPR‐Cas9 LDHA or LDHB knock‐outs have limited effects on glioblastoma development, while major biological adaptations are observed in double LDHA/B KO cells." (PMID 36278433, 2022). "Next, we determined the impact of Aurora kinase A on key glycolytic transporters (SLC2A1) and enzymes (HK2, LDHA), some of which are upregulated in glioblastoma as compared to normal brain tissue." (PMID 34471141, 2021). "To inhibit TGF-β1-induced glycolysis, we treated glioblastoma cells with siRNA against LDHA (siLDHA), which was the most highly upregulated glycolytic gene under treatment with TGF-β1." (PMID 34257808, 2021). "MB, CAIX, and LDHA in normal brain tissues microarrays of glioblastoma multiforme, and cancer adjacent normal tissue." (PMID 33996536, 2021).
glioblastoma (continued). "MV-Edm infection upregulates glycolysis under aerobic conditions (the Warburg effect) in glioblastoma cells, which was evidenced by increased glucose uptake, lactate production, and LDHA expression upon MV-Edm infection." (PMID 25575816, 2015). "To further confirm the relevance of LDHA-mediated tumor glycolysis in promoting macrophage infiltration, we conducted shRNA-mediated LDHA depletion (shLdha) in glioblastoma cells, such as CT2A and GL261, or treated them and GSCs with LDHA inhibitors (e.g., stiripentol and FX11)." (PMID 38443336, 2024). "Finally, this phenomenon was reinforced by a scratch assay showing that CT2A CM-induced macrophage migration was impaired when glioblastoma cell LDHA was inhibited genetically and pharmacologically." (PMID 38443336, 2024). "Moreover, bioinformatics analyses in TCGA glioblastoma dataset confirmed that LDHA, YAP1, STAT3, CCL2, and CCL7 positively correlated with each other and with macrophage signature in patient tumors." (PMID 38443336, 2024). "Moreover, depletion of LDHA in glioblastoma cells or treatment with LDHA inhibitor stiripentol reduced pro-tumor CD45highCD11b+CD68+CD206+ macrophages in tumors from CT2A-bearing mice." (PMID 38443336, 2024). "Moreover, the median survival time of glioblastoma patients with high plasma LDHA (389 days) was lower than the patients with low plasma LDHA (675 days)." (PMID 38443336, 2024). "Together, the identification of tumor-macrophage symbiosis, coupled with the anti-tumor effect of LDHA inhibition in glioblastoma mouse models and clinical validations, encourages the development of therapeutic strategies targeting this symbiosis in glioblastoma patients." (PMID 38443336, 2024). "As a result, we found that EMφ CM promoted LDHA expression in CT2A and GL261 cells, prompting a speculation that TAMs may support glioblastoma cell growth and survival via upregulating LDHA." (PMID 38443336, 2024). "Similarly, LDHA-high glioblastoma patient tumors showed prominent representations of leukocyte and myeloid cell migration signatures, immune response networks, and cytokine and chemokine signatures." (PMID 38443336, 2024). "Since LDHA, CCL2 and CCL7 are genes encoding secreted proteins, we compared their protein levels in patient plasma showing that all of them were higher in glioblastoma patients than that in healthy controls, but such levels were not changed in meningioma patients." (PMID 38443336, 2024). "In summary, our work reveals that glioblastoma cell glycolysis triggers the infiltration of macrophages into the TME via upregulating LDHA-regulated CCL2/CCL7, and reciprocally, macrophages promote tumor growth and survival via EVs delivering LDHA to glioblastoma cells." (PMID 38443336, 2024). "In this work, we elucidate the essential role and molecular mechanism of glioblastoma cell LDHA in promoting macrophage infiltration into the TME and reveal the co-dependencies for macrophage-derived extracellular vesicles (EVs) in supporting glioblastoma cell glycolysis, growth, and survival." (PMID 38443336, 2024). "Chesnelong and colleagues found low expression and high methylation of LDHA in IDHmt glioblastomas." (PMID 36142793, 2022). "Several authors have reported on the significance of glioblastoma LDHA expression." (PMID 36142793, 2022). "LDHA (lactate dehydrogenase A) is frequently upregulated in clinical tumors to support the high glycolytic activity, and high expression has been thought to be responsible for many cancers, such as glioblastoma, pancreatic, and some kidney cancers." (PMID 31835667, 2019). "Therefore, our current work reveals the molecular mechanisms underlying tumor-macrophage symbiosis and supports the hypothesis that targeting this LDHA-mediated symbiosis could provide clinical benefits for glioblastoma patients." (PMID 38443336, 2024).
glioblastoma (continued). "GSEA on KEGG pathways of CT2A cells with FX11 treatment versus control exhibited a prominent reduction of signatures related to chemokine and cytokine-cytokine receptor interaction, suggesting that LDHA in glioblastoma cells may regulate the expression of chemokines and cytokines." (PMID 38443336, 2024). "To further investigate whether LDHA-regulated lactate contributes to this process, we treated LDHA-depleted glioblastoma cells with lactate and found that this treatment rescued the impaired signaling of P-ERK, YAP1, P-STAT3, CCL2, and CCL7 in shLdha CT2A cells." (PMID 38443336, 2024). "To investigate whether LDHA could be delivered from macrophages into glioblastoma cells via EVs, we treated EMφ with GW4869 (an EV biogenesis and release inhibitor) and found that this treatment abolished EMφ CM-induced LDHA upregulation in both CT2A and GL261 cells." (PMID 38443336, 2024). "Thus, LDHA-mediated tumor-macrophage symbiosis provides therapeutic targets for glioblastoma." (PMID 37886538, 2023). "Mechanistically, LDHA-lactate-directed ERK pathway activates YAP1 and STAT3 transcriptional co-activators to upregulate CCL2 and CCL7 in glioblastoma cells, which promote macrophage infiltration into the TME." (PMID 38443336, 2024). "Together, these findings suggest that YAP1 and STAT3 transcriptional co-activators contribute to LDHA/lactate–ERK axis-dependent CCL2 and CCL7 expression in glioblastoma cells." (PMID 38443336, 2024). "Mechanistically, our study demonstrated that these two chemokines are regulated by LDHA/lactate-induced activation of YAP1 and STAT3 in glioblastoma cells." (PMID 38443336, 2024). "Together, these findings suggest that LDHA-directed ERK pathway regulates HOXA9, YAP1, and STAT3 transcription factors and/or signaling pathways in glioblastoma cells and GSCs." (PMID 38443336, 2024). "Recent studies have shown that LDHA activates two transcriptional co-activators, yes-related protein 1 (YAP1) and transcriptional activator 3 (STAT3), in glioblastoma cells through a directed extracellular signal-regulated kinase (ERK) pathway." (PMID 39464313, 2024). "Hexokinase II (HKII), lactate dehydrogenase A (LDHA), sirtuin 4 (SIRT4), and glutamine synthetase (GS) have been shown to be elevated in glioblastomas." (PMID 36768856, 2023). "Castells and colleagues reported that the expression values from only four transcripts (CHI3L1, LDHA, LGALS1, and IGFBP3) were able to distinguish two survival groups in Glioblastoma." (PMID 27121858, 2016). "Indeed, it was recently shown that the combined deletion of LDHA and LDHB in human glioblastoma xenografts prolongs survival after RT60." (PMID 40090955, 2025). "Based on the nature (e.g., well-tolerated in patients and BBB penetrating ability) of the two compounds, coupled with their anti-tumor effect in glioblastoma mouse and PDX models, we anticipate a tremendous translational potential of LDHA inhibition to improve patient outcomes." (PMID 38443336, 2024). "To confirm the role of LDHA in regulation of the YAP1/STAT3–CCL2/CCL7 signaling axis in vivo, we performed immunofluorescence for YAP1 and STAT3 in tumors and ELISA for CCL2 and CCL7 in plasma from control and LDHA-inhibited glioblastoma tumor-bearing mice." (PMID 38443336, 2024). "The decreased P-ERK, YAP1, P-STAT3, CCL2, and CCL7 in LDHA-depleted glioblastoma cells was rescued by the treatment with EMφ EVs, but not LDHA-depleted EMφ EVs." (PMID 38443336, 2024). "Moreover, plasma LDHA correlated positively with plasma CCL2 and CCL7 and intratumoral macrophages in glioblastoma." (PMID 38443336, 2024). "Thus, a positive correlation between p21 and HIF-1α enhances GLUT-1/lactate dehydrogenase A (LDHA) mediated glycolysis and exacerbates glioblastoma radioresistance." (PMID 36157351, 2022). "Besides, genetic inhibition of LDHA and PDK1 reversed the TGF-β1-induced glioblastoma cells' migration and invasion." (PMID 34257808, 2021).
glioblastoma (continued). "Similarly, glioblastoma cells treated with GSK2837808A (GSK, 10 μM), a selective inhibitor of LDHA and Dichloroacetate (DCA, 20 μM), a selective inhibitor of PDK1, reversed the EMT protein markers induced by TGF-β1." (PMID 34257808, 2021). "The U251 glioblastoma line did not express detectable levels of LDHA, whereas all other lines tested expressed micromolar levels of LDHA protein." (PMID 24280423, 2013). "Excitingly, a natural micropeptide that localizes to mitochondria where it interacts with LDHA and LDHB to prevent the conversion of lactate to pyruvate was also recently identified and shown to inhibit the growth and tumorigenicity of patient-derived primary glioblastoma cells." (PMID 40090955, 2025). "However, the potential link between immune cells and LDHA-mediated tumor glycolysis in glioblastoma has not been established." (PMID 38443336, 2024). "Notably, we found that the impaired glycolytic activity as shown by reduced ECAR in LDHA-depleted glioblastoma cells was negated by the treatment with EVs from EMφ, but not LDHA-depleted EMφ." (PMID 38443336, 2024). "However, LDHA in glioblastoma cells was upregulated upon uptake of EVs from shC EMφ, but not from LDHA-depleted EMφ." (PMID 38443336, 2024). "Therefore, targeting LDHA-mediated tumor-macrophage symbiosis using the BBB penetrable compounds (e.g., stiripentol and isosafrole) is a promising strategy for treating patients with glioblastoma." (PMID 38443336, 2024). "In fact, Koukourakis et al55 sensitized glioblastoma cell lines, namely the most resistant ones, to conventional therapies (radiotherapy and chemotherapy with TMZ), using the glycolytic inhibitor 2‐DG and the LDHA inhibitor oxamate, as well as LDHA gene silencing." (PMID 29845734, 2018). "EGFR activates ERK1/2-dependant nuclear translocation of PKM2 and activates Myc, which in turn up-regulate GLUT1, LDHA and PKM2 expression in human glioblastoma multiforme (GBM) cells." (PMID 26147004, 2015). "Moreover, plasma LDHA, CCL2, and CCL7 levels were not related to the status of recurrence, gender, age, and MGMT methylation in glioblastoma patients." (PMID 38443336, 2024).